EGFR (epidermal growth factor receptor)
Diseases named in the same sentence as EGFR in open-access papers (continued):
Sharing a sentence is not in itself a finding about the gene and the disease.
breast carcinoma (continued). "Despite the recognition that EGFR overexpression in breast tumors may affect disease progression, the responses of anti-EGFR therapies in breast cancer are not fully satisfactory, and the reasons for this clinical variability are not fully understood." (PMID 24629097, 2014). "Moreover, TAM and G1 induced CYP19A1 gene expression and increased E2 production, also via the GPER/EGFR/ERK pathway, providing novel insights into the estrogenic effects on the breast cancer microenvironment and the induction of TAM resistance in a CAF-dependent manner." (PMID 24481325, 2014). "We recently reported that the novel investigational EGFR/HER2 kinase inhibitor TAK-285, which has anti-tumor activity and penetrates the rat blood-brain barrier, might be used for the treatment of HER2-overexpressing metastatic breast cancers." (PMID 25594012, 2014). "Thus there was co-expression of EGFRvIII and EGFR WT in some human invasive breast cancer tissue but not in normal breast samples." (PMID 25051360, 2014). "Studies demonstrated weakly inhibiting EGFR tumor suppression activity in SK-OV-3 cell lines when HER2 knockdown occurred in vivo, and potent tumor suppression was exhibited in HER2-overexpressing adenocarcinoma xenograft and FVB-2/N(neu) transgenic breast cancer mouse models." (PMID 25251190, 2014). "Moreover, EGFR expression correlated with CXCR7 expression across breast cancer cell lines and no EGFR expression was observed in the cell lines that lack CXCR7 protein expression." (PMID 25168820, 2014). "Interestingly, in breast cancer cells the synthesis and release of CXCL12 is under the control of 17β-estradiol contributing to its proliferative effects and mediating, via a Src-dependent mechanism, EGFR transactivation." (PMID 25484899, 2014). "Triple negative breast cancer (TNBC) is a subtype of breast cancer that shares with the basal-like group many of its characteristics and GEP markers, including expression of basal cytokeratins 5/6, 14, and 17, as well as the epidermal growth factor receptor (EGFR) and vimentin." (PMID 24244833, 2013). "In addition to low expression of ER, PR and HER2, basal-like breast cancers are characterized by a high expression of CK5, CK14, caveolin-1, caix, p63, EGFR (Epidermal Growth Factor Receptor)/HER1, which reflects on the mammary gland basal/myoepithelial cell component." (PMID 25285241, 2013). "In breast-cancer cells, resveratrol has been reported to inhibit migration and invasion of cells through the suppression of the activation of PI3K/Akt signaling pathway, and epidermal growth factor (EGF)-induced migration, presumably through the EGFR/PI3K signaling pathway." (PMID 23457620, 2013). "Therefore, we hypothesized that co-inhibition of EGFR and IGF-1R would further impact the response of breast cancer cells to irradiation." (PMID 23777562, 2013). "Interestingly, EGFR expression is weak or undetectable in MCF10DCIS.com xenografts, suggesting that EGFR is not obligatory for the pathogenesis of this basal-like breast cancer subtype." (PMID 23548208, 2013). "As a control, human MDA-MB453 breast carcinoma cells were included, which are negative for EGFR." (PMID 23573299, 2013). "Interestingly, HER3 overexpression has been shown to have negative effects on breast cancer survival among patients with EGFR/HER1 and HER2 non-amplified tumours." (PMID 23991224, 2013). "In human breast cancer cell lines with amplified ERBB2 expression, depletion of ERBB3 reduces cell proliferation to the same extent as depletion of ERBB2, while loss of ERBB1 (epidermal growth factor receptor (EGFR)) does not affect proliferation." (PMID 23593223, 2013). "The inhibition of EGFR phosphorylation is crucial in breast cancer, however, whether the changes seen in the downstream signaling pathways are in-part due to the lack of EGFR phosphorylation needs further investigation." (PMID 24059654, 2013).
breast carcinoma (continued). "Furthermore, the expression of the EGFR is twice as likely in breast cancers which are “double negative”, lacking both the ER and the progesterone receptor (PR)." (PMID 23434903, 2013). "Similarly, afatinib is an irreversible inhibitor of EGFR and HER2, with preliminary evidence of activity in the phase II non-CNS metastatic setting, which is currently in clinical trials for the treatment of breast cancer brain metastases." (PMID 23662165, 2013). "Breast cancers do not respond to EGFR TKIs, even though EGFR is overexpressed." (PMID 22788954, 2012). "Thus, we speculated that EBP50 might mask the EGFR phosphorylation site to suppress EGFR downstream signaling activation, thereby hinder EGF-induced proliferation of breast cancer cells." (PMID 22476347, 2012). "Therefore the panel EGFR, MET, HER2, GLUT1, CAIX, and IGF1-R detected 84.2% of the basal/TN ductal breast cancers compared to 45.0% of the luminal-type, and 18.3% of the lobular breast cancer cases." (PMID 22695343, 2012). "The nanobioconjugate carries anti-tumor nucleosome-specific monoclonal antibody (mAb) 2C5 to target breast cancer cells, anti-mouse transferrin receptor (TfR) antibody for drug delivery through the host endothelial system, and Morpholino antisense oligonucleotide (AON) to inhibit EGFR synthesis." (PMID 22355336, 2012). "One cytotoxic isoform, RBM5 + 5 + 6 t, was downregulated in breast cancer cells (both primary tumors and a cell line) that have overexpressed HER2, which suggested that factors in the EGFR pathway may function as upstream modulators of RBM5 function and/or expression." (PMID 22537942, 2012). "This intrinsic resistance to EGFR TKIs in breast cancer does not correlate with Met amplification." (PMID 22788954, 2012). "To date, it is most appropriate to define ER, PR, HER2, CK 5/6 and EGFR as the immunohistochemical markers for basal like subtype, which implied that triple negative was the main feature of basal like breast cancer for a lack of expression of ER, PR and HER2 by IHC." (PMID 23046633, 2012). "However, 50–75% of basal breast cancers express EGFR and are more aggressive than similar tumors lacking the receptor." (PMID 22276166, 2012). "In search of the minimal panel of targeted probes needed for the highest possible detection rate, we showed that 80% of all breast cancers express at least one of a panel of membrane markers (CD44v6, GLUT1, EGFR, HER2, and IGF1-R) that may therefore be suitable for molecular imaging strategies." (PMID 22695343, 2012). "Moreover, AEE788 (a combined inhibitor of EGFR, HER2 and VEGFR) plus tamoxifen or letrozole in breast cancer overexpressing HER2, may provide superior anti-tumour activity, compared with single agents." (PMID 23344024, 2012). "By gene expression profiling and IHC markers, breast cancers can be classified into five major subtypes: luminal A (ER + and/or PR+, HER2-), luminal B (ER + and/or PR+, HER2+), HER2-overexpressing (ER-, PR-, HER2+), basal-like (ER-, PR-, HER2-, CK5/6+ and/or EGFR+) and normal breast-like tumors." (PMID 23009686, 2012). "From these observations, we conclude that AnxA2 is involved in EGFR downstream signaling, either directly or indirectly, in a Src dependent manner and significantly contributes to the survival, growth and progression of Her-2 negative breast cancer." (PMID 22957061, 2012). "The multifunctions of curcumin in downregulating EGFR and HER-2 oncoproteins, reducing the phosphorylation of Akt and MAPK and suppressing NF-κB activation, led to interest in using curcumin in the treatment of HER-2-overexpressed breast cancer, along with herceptin and/or taxol." (PMID 21876713, 2012). "We speculated that EBP50 masked the EGFR phosphorylation site via steric hindrance, resulting in the retardation of EGFR downstream signaling activation, thus suppressed EGF-induced proliferation of breast cancer cells." (PMID 22476347, 2012).
breast carcinoma (continued). "Most TN breast cancers fit within the basal-like subgroup, although these two terms are not synonymous, and immunohistochemical assessment of EGFR and basal cytokeratins 5 and 6 is usually needed for better profiling of the basal-like phenotype among the TN tumors." (PMID 22555942, 2012). "Our data here support the hypothesis that this lack of efficacy in clinical treatment of breast cancers with EGFR TKIs is due to crosstalk between EGFR and Met." (PMID 22788954, 2012). "Functional interaction research in breast cancer indicates that breast cancer metastasis suppressor 1 (BRMS1) up-regulates miR-146a and b; expression of either miRNA resulted in down-regulation of epidermal growth factor receptor (EGFR) and reduced invasion, migration, and metastasis." (PMID 23335942, 2012). "Breast cancers that first give rise to lung metastases very often express either EGFR or HER2, which suggests that such cancers might be a potential target group for dual HER1 and HER2 inhibitors, such as lapatinib or neratinib." (PMID 21914172, 2011). "EGFR mutations and KRAS mutations either do not occur or are exceptional in breast cancer." (PMID 21966417, 2011). "Since our data revealed that Kp-10 does not act as a chemoattractant to stimulate breast cell migration, we investigated whether or not GPR54 may crosstalk with EGFR to regulate breast cancer cell invasion." (PMID 21738726, 2011). "It has been shown that a pool of ERα resides in or associates with the plasma membrane and utilizes the membrane EGFR to rapidly signal through various kinase cascades that influence both transcriptional and non-transcriptional actions of estrogen in breast cancer cells." (PMID 21124760, 2010). "Thus, in addition to the (IL12, TGFB) interaction, we observed that high EGFR and low IL12 activity provided a better prognostic model in ER- breast cancer, while simultaneous high MYC high RAS activity defined a better prognostic model in ER+ breast cancer." (PMID 21050467, 2010). "An interesting application of the aptamer as demonstrated by these authors is that gold nanoparticles (GNP) coated with the anti-EGFR aptamer were specifically targeted and internalized into high EGFR-expressing cell line A431 but not the low EGFR-expressing breast cancer cell line MDA-MB-435." (PMID 27713328, 2010). "Therefore, to avoid unspecific variations due to RNA degradation, we developed a corrective algorithm that take into account the RNA integrity of each sample and we validated the proposed model through the quantification of EGFR, HER2 and HER3 mRNA in colon and breast cancer cell lines." (PMID 19368728, 2009). "The potential role for serum EGFR assessments in breast cancer is not quite as clear, however." (PMID 17976236, 2007). "The lack of clinical response in breast cancers treated with gefitinib in vivo has been partially attributed to activation of this pathway downstream of EGFR, or ineffective methods of identifying those tumors that show an EGFR-dependent signature." (PMID 17663798, 2007). "Thus, in contrast to other reports, we did not observe any effect of either EGFR/Her2 or Src inhibition on Stat3 activation in breast cancer-derived cell lines." (PMID 17531096, 2007). "In light of these results, we asked whether WNT ligands induce EGFR/ERK1/2 activation in human breast cancer cells in a fashion similar to that in non-transformed mouse mammary epithelial cells." (PMID 17897439, 2007). "Thus, receptor interactions involving HER2 may play key roles in breast cancer cells that both overexpress HER2 and express the EGFR." (PMID 16622439, 2006). "More recently, a study by Greco and colleagues conducted in MCF-7 cells and primary breast cancer cells revealed that AT1 receptor regulates mitogenic signalling pathways by two simultaneous mechanisms, one involving protein kinase C and the other EGFR transactivation." (PMID 16805920, 2006).
breast carcinoma (continued). "The combination of AEE788 (a dual TKI of EGFR/HER-2 and inhibitor of the VEGF receptor) and letrozole has been shown to enhance growth inhibition in ER+ breast cancer cell lines compared with either drug alone, but this activity may be restricted to tumours that overexpress EGFR and/or HER-2." (PMID 16926831, 2006). "Phosphorylation of EGFR and the remaining kinases were all correlated with PDK-1 phosphorylation (P<0.05), suggesting that EGFR might be one of the upstream regulators whereas other remaining kinases are downstream of PDK-1 pathway in breast carcinoma." (PMID 16288304, 2005). "IGFBP-3 regulates breast cancer epithelial growth through IGF-dependent and IGF-independent pathways that involve both growth inhibition and enhanced apoptosis with the potential to switch to growth stimulatory pathways interacting with EGFR, HER-2 and fibronectin." (PMID 15642160, 2005). "However, EGFR, a mRNA marker gene described for circulating tumour cell detection in peripheral blood of breast cancer patients, appeared not to be applicable as a marker gene in lymph nodes due to its high background expression in control lymph nodes." (PMID 15083181, 2004). "EGFR mRNA was detected in 55% of breast cancers and in all non-neoplastic breast tissue tested." (PMID 2331446, 1990). "Notably, immunoblot analysis revealed significantly enhanced EGFR activation in hepatotropic metastatic cells (HM3) compared to Pri cells, brain-tropic (BM3), and lung-tropic (LM3) derivatives, indicating organotropism-dependent EGFR hyperactivation in breast cancer liver metastases." (PMID 41513618, 2026). "Furthermore, upregulated of ROS related signatures are observed in residual tumors from TKI‐treated patients with EGFR+ NSCLC, HER2+ breast cancer, and BRAF+ melanoma, suggesting that the findings of our study with ALK+ NSCLC cells may also possibly be observed in patients with ALK+ NSCLC." (PMID 39369284, 2025). "However, RAS/MAPK pathway activity is linked to breast cancer progress and maybe dysregulated by overexpression of upstream receptor tyrosine kinases such as human epidermal growth factor receptors 1 and 2 (aka HER1 and HER2), as commonly observed in breast cancer." (PMID 40487641, 2025). "Further, a recent high throughput screen using breast cancer PDX models with PI3K mutations found that afatinib and alpelisib were synergistic, which confirms our data, however they did not compare the synergy of models with both EGFR amplification and PI3K mutations to those without." (PMID 40501689, 2025). "While blocking the EGF receptor by a mAb does not lead to clinical benefit so far, we hypothesized that EGFR remains a valid target for drug delivery systems in breast cancer, due to the high frequency and expression levels of EGFR on the surface of TNBC tumor cells." (PMID 36879012, 2023). "However, EGFR inhibitors have not achieved satisfactory clinical results in breast cancer." (PMID 38114991, 2023). "Their study demonstrated that Luteolin could suppress the EGF-induced activities of EGFR signaling in human breast cancer cell lines and suggested that STAT3, MAPK/ERK1/2, and PI3K/Akt signaling pathways are the main pathways through which Luteolin exhibits its effects on EGFR signaling." (PMID 36992138, 2023). "Finally, in the two cell lines that displayed aerotaxis independently of EGFR activation but stimulated by EGF, one was Basal A and the other was Basal B. Based on this analysis, the molecular subtypes of breast cancer cell lines do not seem to be linked to their aerotactic profiles." (PMID 36380366, 2022). "Interestingly, blocking the SRC/EGFR-dependent ITGB4/FAK pathway, which subsequently inactivates the Akt and p38/MAPK pathways contributes to the suppression of migration and invasiveness of breast cancer cells and reversal of EMT process after treatment with Ziyu II." (PMID 35379785, 2022).
breast carcinoma (continued). "Additionally, increased UCH-L1 levels in advanced breast cancer patients who did not respond to chemotherapy led to overexpression of epidermal growth factor receptor (EGFR) and an increase in cancer cell invasion, metastasis and shortened the rate of survival." (PMID 36233276, 2022). "However, no EGFR-targeted mAbs are currently approved for the treatment of breast cancer." (PMID 33804477, 2021). "Recently, an Fc-fusion EGFR decoy comprising the truncated extracellular domains of EGFR/ErbB-1 and ErbB-4 fused to Fc was shown to have high-affinity ligand binding to EGF-like growth factors and could inhibit the invasive growth and metastasis of mammary carcinoma cells." (PMID 32365498, 2020). "The detection of these three phosphorylated proteins (EGFR, MSK1/2, CREB) strongly supports a functional consequences marked by EGF pathway transcriptional activity in response to toxic agents which could be an important early step in breast cancer development." (PMID 32466334, 2020). "As SHIP2 and SYNJ2 both contribute to EGFR turnover, future studies should investigate whether PIPP also regulates receptor trafficking, as another mechanism by which this 5-phosphatase differentially regulates breast cancer progression, especially as PIPP is also recruited to membrane ruffles." (PMID 33276499, 2020). "Likewise, 2OHOA induces FasR clustering and its ligand-free activation in leukemia cells, indicating that this redistribution of EGFR could influence its activation in the absence of agonist ligands in these breast cancer cells." (PMID 31069012, 2019). "Hence, EGFR is one of the important targets for HER2 negative breast cancer including TNBCs." (PMID 29455658, 2018). "As HER2 and EGFR can activate Akt (although HER2 would be its dominant activator in breast cancer) and Akt in turn can promote cell survival, the observed inhibition of cell growth following JAM-A knockdown in drug-resistant models may reflect downregulation of HER2, EGFR, and pAkt." (PMID 30458861, 2018). "In a number of breast cancer cell lines, cIAP1 depletion also resulted in a reduction of EGFR protein levels which derived from the decrease of its gene transcription, though, paradoxically, the silencing of cIAP1 promoted EGFR protein stability rather than its degradation." (PMID 29674627, 2018). "Therefore, EGFR blockade with Th1 cytokines may offer a treatment approach in TNBC, where tumor cells grow rapidly and recurrence is significantly faster than other sub-types of breast cancers." (PMID 29796172, 2018). "Indeed, an increased EGFR co-localization with the early endosomes marker EEA.1 could be detected in MCF-7 and MDA-MB-231 cells treated with Akt1 siRNA, suggesting that PIKfyve activity was inhibited when Akt1 was knocked down in breast cancer cells." (PMID 30445978, 2018). "However, remaining CTCs in these breast cancer patients revealed negative for EGFR, which pinpoints at possible escape mechanisms that could be addressed through the use of multiple targeted treatments." (PMID 27683128, 2017). "The identification of EGFR as a target of the ZNF516–CtBP/LSD1/CoREST complex and the well-documented role of EGFR in the development and progression of of various malignancies suggest that the ZNF516–CtBP/LSD1/CoREST complex may also function in breast cancer growth and metastasis." (PMID 28947780, 2017). "Here, we compare clinicopathological information and the expression of a panel of IHC markers (ER, PR, HER2, EGFR, CK 5/6, CK14, CK17, c-Kit and Ki67) with the ADAM33 protein scores to determine whether ADAM33 protein is clinically efficient as a prognostic or predictive marker for breast cancer." (PMID 28294120, 2017). "However, in breast cancer cells, FRK suppresses cell proliferation by arresting cells in the G1 phase of the cell cycle; regulating PTEN protein stability and function; inhibiting EGFR signaling, and by regulating the stability and potentially the tumor suppressor function of BRCA1 protein." (PMID 29348886, 2017).